SAMD5 (sterile alpha motif domain containing 5)
Synonyms: dJ875H10.1
Tractability: No criterion of Open Targets' tractability assessment is met for any kind of drug.
Gene: Protein-coding gene on chromosome 6 (147,508,690 to 147,737,547, forward strand). Ensembl gene ENSG00000203727.
Subcellular location: Cytoplasm
Subcellular location (Human Protein Atlas): Vesicles
Gene Ontology:
Biological process: regulation of intracellular signal transduction
Cellular component: cytoplasm
Genetic constraint (gnomAD): Loss-of-function variants: 8 observed, 7.65 expected, observed/expected ratio (o/e) 1.05, 90% interval 0.61 to 1.76. That is too few expected variants to judge how well the gene tolerates losing a copy. Missense variants: 233 observed, 183.58 expected, observed/expected ratio (o/e) 1.27, 90% interval 1.14 to 1.41. Synonymous variants: 123 observed, 86.86 expected, observed/expected ratio (o/e) 1.42, 90% interval 1.22 to 1.64.
Homologues: Orthologues: chimpanzee SAMD5 (99% identical), macaque SAMD5 (95% identical), pig SAMD5 (91% identical), guinea pig SAMD5 (90% identical), mouse Samd5 (89% identical), dog SAMD5 (87% identical), rat Samd5 (82% identical), zebrafish SAMD5 (52% identical).
Diseases named in the same sentence as SAMD5 in open-access papers:
SAMD5 is named in the same sentence as 22 diseases in open-access papers, as found by Europe PMC text mining. Sharing a sentence is not in itself a finding about the gene and the disease. The quoted sentences say what the papers report.
rectal cancer (3 papers, 2014 to 2024). A primary or metastatic malignant neoplasm that affects the rectum. "SAMD5 has been reported to be one of 24 discriminating genes with an expression level that significantly differs between responders and nonresponders to chemoradiotherapy in rectal cancer." (PMID 25411851, 2014).
breast carcinoma (2 papers, 2018 to 2024). "SAMD5 acts as a tumor suppressor in breast cancer, particularly in TNBC, by inhibiting critical cellular processes and downregulating the c-Myc signaling pathway." (PMID 39524172, 2024). "Targeting the SAMD5/PLK1 axis offers a promising therapeutic strategy for addressing aggressive breast cancers." (PMID 39524172, 2024). "SAMD5 expression levels were shown to be dramatically decreased in breast carcinoma tissue samples and cells compared to adjacent normal tissue samples and non-cancerous breast epithelial cell lines." (PMID 39524172, 2024). "Herein, using online datasets, differentially expressed genes (DEGs) in breast cancer samples were identified, and Sterile Alpha Motif Domain-Containing 5 (SAMD5) was found." (PMID 39524172, 2024). "Herein, integrative bioinformatics analysis identified SAMD5 as a dramatically decreased factor in breast carcinoma tissue samples and cells." (PMID 39524172, 2024). "In this study, SAMD5 was proven to be a significantly downregulated factor in breast carcinoma by integrative differential expression analysis, with a close correlation with the c-Myc signaling." (PMID 39524172, 2024). "The GSE21444 dataset, which includes an animal model of breast cancer induced by oncogenic transcription factors, supported the significant downregulation of SAMD5 (log2FC = -5.055, p = 2.80 × 10-5)." (PMID 39524172, 2024). "Regarding the mechanisms underlying the tumor suppressive effects of SAMD5, PLK1 has been found to be negatively correlated with SAMD5 in breast cancer." (PMID 39524172, 2024). "The findings presented here not only enhance our understanding of breast cancer biology but also highlight the potential of the SAMD5/PLK1 axis as a therapeutic target." (PMID 39524172, 2024). "In this study, we explored the role of Sterile Alpha Motif Domain-Containing 5 (SAMD5) as a potential regulatory partner with the c-Myc oncogenic signaling pathway in breast cancer." (PMID 39524172, 2024). "More importantly, SAMD5 is negatively correlated with c-Myc signaling, a critical signaling pathway facilitating breast cancer development, suggesting its potential as a tumor suppressor in breast carcinoma." (PMID 39524172, 2024). "Regarding cell phenotypes, PLK1 overexpression facilitated cell viability, colony formation, and invasive capability; additionally, PLK1 overexpression partially attenuated the effects of SAMD5 overexpression on cell viability, colony formation, and cell invasion in breast cancer cells." (PMID 39524172, 2024). "Since SAMD5 negatively correlates with PLK1, the dynamic effects of SAMD5 and PLK1 on breast cancer cells were explored to investigate whether PLK1 mediates SAMD5 functions in breast cancer." (PMID 39524172, 2024). "The expression and functions of SAMD5 in breast cancer cells were investigated." (PMID 39524172, 2024). "After confirming the downregulation of SAMD5 in breast cancer, SAMD5 overexpression was achieved in two TNBC cell lines (MDA-MB-231 and HCC1937) by introducing SAMD5 overexpression and validated using RT-qPCR and immunoblotting for further functional investigations." (PMID 39524172, 2024). "Therefore, PLK1 may mediate the functions of SAMD5 in breast cancer cells." (PMID 39524172, 2024). "Knockdown of PLK1 in breast carcinoma cell lines suppressed cell viability, colony formation, and invasion, while PLK1 overexpression attenuated the inhibitory effects of SAMD5 overexpression." (PMID 39524172, 2024). "Consistently, SAMD5 overexpression markedly reduced Ki67, MMP2, and MMP9 protein levels in breast cancer cells relative to the control group." (PMID 39524172, 2024). "Mechanistic studies indicated that SAMD5 negatively correlated with PLK1, a gene overexpressed in breast carcinoma, especially in triple-negative subtypes." (PMID 39524172, 2024).
breast carcinoma (continued). "More importantly, PLK1 overexpression significantly attenuated the tumor-suppressive effects of SAMD5 overexpression on aggressive breast carcinoma cell phenotypes, suggesting that PLK1 mediates the functions of SAMD5 in breast cancer." (PMID 39524172, 2024). "SAMD5 regulation of PLK1 was validated, and the dynamic effects of SAMD5/PLK1 on breast cancer cell phenotypes, c-Myc signaling, and in vivo tumor growth in a mouse model were explored." (PMID 39524172, 2024). "Another promising candidate is SAMD5, whose SAM domain is similar to SHIP2 SAM and highly expressed in breast cancer cells and mainly cytoplasmic." (PMID 29749928, 2018). "In vivo studies using a xenograft tumor model in nude mice demonstrated that SAMD5 overexpression reduced tumor weight and volume, with these effects being partially reversed by PLK1 overexpression, highlighting the interaction between SAMD5 and PLK1 in modulating breast carcinoma progression." (PMID 39524172, 2024). "Mechanistic analyses identified a negative correlation between SAMD5 and Polo-like Kinase 1 (PLK1), a gene frequently overexpressed in breast cancer, particularly in TNBC." (PMID 39524172, 2024).
cholangiocarcinoma (2 papers, 2017 to 2024). A carcinoma that arises from the intrahepatic biliary tree (intrahepatic cholangiocarcinoma) or from the junction, or adjacent to the junction, of the right and left hepatic ducts (hilar cholangiocarcinoma). "Knockdown and overexpression studies further implicated SAMD5 in regulating the cell cycle and proliferation in cholangiocarcinoma cells." (PMID 39524172, 2024). "IHC analysis indicated the expression of SAMD5 in human biliary epithelial cells (BECs) and cholangiocarcinoma, where it localizes to the nucleus in cancer cells and the cytoplasm in normal cells, suggesting active nuclear transport in cancer." (PMID 39524172, 2024). "However, the expression profile and role of SAMD5 in biliary diseases including cholangiocarcinoma (CC) remain totally unknown." (PMID 28388653, 2017).
prostate carcinoma (2 papers, 2020 to 2021). A carcinoma that arises from epithelial cells of the prostate gland. "SAMD5 mRNA has been reported to be up-regulated in prostate cancer samples, and its high expression is related to poor prognosis after radical prostatectomy." (PMID 33371778, 2021). "A study found that SAMD5 was overexpressed in prostate cancer and had powerful prognostic ability for predicting post-operative biochemical recurrence after radical prostatectomy." (PMID 32475352, 2020). "In the context of disease-related anomalies, a study found that SAMD5 was overexpressed in prostate cancer and had powerful prognostic ability on predicting post-operative biochemical recurrence after radical prostatectomy." (PMID 32475352, 2020).
bladder cancer (1 paper, 2021). "In conclusion, KCNMB2-AS1 mediated the bladder cancer cells progress by regulating the miR-3194-3p/SAMD5 signal pathway, which would provide a new target for bladder cancer research." (PMID 34026626, 2021). "Further evidence was found overexpression of SAMD5 would recovery the stemness of bladder cancer." (PMID 34026626, 2021).
Cholestatic liver disease (1 paper, 2017). "Using a mouse model of cholestatic liver disease, we demonstrated that SAMD5 expression was upregulated in the large bile duct at the hepatic hilum, the extrahepatic bile duct and PBGs, but not in proliferating intrahepatic ductules, suggesting that SAMD5 is expressed in BTSC but not LPC." (PMID 28388653, 2017).
chordoma (1 paper, 2017). Chordomas are rare malignant tumors arising from embryonic remnants of the notochord in axial skeleton. "We found that chordoma group has significantly higher SAMD5 expression level compared to the other major cancers, further validating its fusion event." (PMID 27901492, 2017).
female infertility (1 paper, 2019). Diminished or absent ability of a female to achieve conception. "SAMD5 is the target of EGR4, which has a well-established role in male infertility but no female infertility due to the arrested spermatogenesis." (PMID 34968233, 2019).
liver diseases (1 paper, 2017). "Although Sterile alpha motif domain containing 5 (SAMD5) was identified as one of such upregulated genes in EpCAM+ cells of DDC-fed mouse liver, the role of SAMD5 in liver diseases remained uninvestigated." (PMID 28388653, 2017).
tubular adenocarcinoma (1 paper, 2017). An infiltrating adenocarcinoma in which the malignant cells form tubular structures. "In addition, the papillary and moderately-differentiated tubular adenocarcinoma in the common bile duct of extrahepatic CC also showed nuclear staining of SAMD5." (PMID 28388653, 2017).
cancer (4 papers, 2017 to 2024). A tumor composed of atypical neoplastic, often pleomorphic cells that invade other tissues. "The biochemical and structural information provided in this study allowed us to test the impact of these mutations found in cancer patients in terms of binding to the cytoplasmic effectors including SHIP2 and SAMD5." (PMID 29749928, 2018). "Given that the localization of SAMD5 in the nucleus is relevant to some characteristics of carcinoma, exogenously expressed SAMD5 in HCC and/or CC cell lines could translocate to the nucleus." (PMID 28388653, 2017).
tumor (4 papers, 2016 to 2024). "In vivo experiments demonstrated that SAMD5 overexpression led to a marked reduction in tumor weight and volume, effects that were partially reversed by PLK1 overexpression." (PMID 39524172, 2024). "Consistently, Ki67, MMP2, MMP9, c-Myc, β-catenin, CDK4, CDK6, and Cyclin D1 protein levels in tumor tissues were significantly decreased by SAMD5 overexpression but partially increased by PLK1 overexpression." (PMID 39524172, 2024). "In vivo, PLK1 also partially abolished the effects of SAMD5 overexpression in inhibiting tumor growth and the c-Myc signaling in a mouse model, providing further evidence for the in vitro findings." (PMID 39524172, 2024). "SAMD5 overexpression significantly decreased tumor weight and volume, whereas PLK1 overexpression partially attenuated these effects." (PMID 39524172, 2024). "In vivo studies were performed using a xenograft tumor model in nude mice to evaluate the impact of SAMD5 overexpression on tumor weight and volume." (PMID 39524172, 2024). "This study identifies SAMD5 as a crucial tumor suppressor in TNBC." (PMID 39524172, 2024). "Furthermore, the correlation of SAMD5 expression levels with tumor purity and infiltration of immune cells was investigated." (PMID 39524172, 2024). "Furthermore, as gene fusion often results in elevated gene expression level, we assessed transcriptome level of SAMD5 in skull base chordoma with different tumor types with available RNAseq data." (PMID 27901492, 2017). "Considering the cytosolic staining of SAMD5 in normal BECs, SAMD5 may originally serve as a tumor suppressor in the cytoplasm." (PMID 28388653, 2017). "Based on Tumor Immune Estimation Resource (TIMER) analysis, SAMD5 expression levels were shown to be positively correlated with cytotoxic natural killer (NK) cell infiltration." (PMID 39524172, 2024). "SAMD5 expression levels were found to exhibit a significant negative correlation with tumor purity (r = -0.306, p = 5.261 × 10-24)." (PMID 39524172, 2024). "Lastly, a xenograft tumor model was established in nude mice, where lentivirus-mediated overexpression of SAMD5 and/or PLK1 was introduced into tumors, and the dynamic effects of SAMD5/PLK1 were investigated." (PMID 39524172, 2024). "The detailed analysis of SAMD5 localization in other tumor cells or overexpression of SAMD5 mutant lacking in nuclear import ability will be useful in dissecting the molecular mechanisms." (PMID 28388653, 2017).
SAMD5 also shares sentences with these, for which no sentence is quoted: infection (2 papers); small cell lung carcinoma (2); depression (1); glaucoma (1); glioma (1); invasive ductal carcinoma (1); lung carcinoma (1); male infertility (1); nephrotic syndrome (1); triple-negative breast carcinoma (1).